FTO (FTO alpha-ketoglutarate dependent dioxygenase)
Diseases named in the same sentence as FTO in open-access papers (continued):
Sharing a sentence is not in itself a finding about the gene and the disease.
Obesity (continued). "Although limited data have been reported in Latino populations, several studies ( GWAS and replication studies) with mixed populations including Latinos have also exhibited the association between FTO genetic variants and obesity measures." (PMID 26908368, 2016). "The findings of our study are important because there are only two other studies thatshow association of FTO rs9930609 with obesity or obesity-relatedtraits and modified lipid profile in a Mexican population." (PMID 27560839, 2016). "Several studies have demonstrated that polymorphisms within the fat-mass and obesity-associated gene (FTO) are associated with type 2 diabetes (T2D)." (PMID 27820839, 2016). "The interaction between leptin and fat mass and obesity-associated (FTO) gene expression is a major mechanistic pathway underlying the role of leptin in the regulation of body-weigh." (PMID 27189377, 2016). "Physical activity (PA) has been shown to reduce the impact of FTO variation and obesity genetic risk scores (GRS) on BMI." (PMID 26727462, 2016). "Here we investigated how FTO and MC4R gene variants linked with obesity relate to patterns of fetal growth and to placental FTO expression." (PMID 26907388, 2016). "While FTO does not seem to play a role in the regulation of physical activity levels, the relationship between FTO and obesity risk is modified by physical activity." (PMID 27846319, 2016). "Text mining system also reported several recently published molecules such as fat mass and obesity associated (FTO) and omega-3 fatty acid receptor 1 (GPR120)." (PMID 26886906, 2016). "Recently, we demonstrated significant heritability estimates of obesity-related phenotypes in our Latino population, and confirmed strong associations to obesity-related traits for the FTO SNPs." (PMID 26908368, 2016). "FTO gene variants are known to associate with obesity but this is the first time that the risk alleles and placental FTO expression have been linked with fetal growth trajectories." (PMID 26907388, 2016). "The association between FTO genetic variants and obesity has been well replicated and established across ethnicities, but the main focus has been on those of European ancestry." (PMID 26908368, 2016). "Obesity associated SNPs in FTO were found to be associated with the expression of IRX3, but not FTO, in the cerebellum of the human brain." (PMID 26907388, 2016). "This has been done for a handful of disorders such as the FTO (fat mass and obesity-associated) locus in obesity, LMO1 (LIM domain only 1) in neuroblastoma predisposition and BCL11A (B-cell lymphoma/leukaemia 11A) in sickle cell anaemia [116•]." (PMID 27628759, 2016). "Not surprisingly, this SNP, rs11075990, is located within the well-established fat mass and obesity-associated gene, FTO on chr 16q12.2." (PMID 27128491, 2016). "We discovered that the FTO gene that encodes an RNA demethylase, which regulates fatness and obesity, is amplified in MA cells." (PMID 27390851, 2016). "This is consistent with the finding that obesity associated SNPs in intron 1 increase FTO expression in humans." (PMID 26828654, 2016). "We have studied the association of FTO polymorphism rs9939609 with obesity and CAD in Pakistani population." (PMID 26878843, 2016). "For instance, SNP in FTO intron causes obesity by long-range functional connection with IRX3, which testifies the causal role of disease-associated SNPs in non-coding region." (PMID 26868054, 2016). "We classify this network into 5 modules and identify new links between the recently discovered fat mass and obesity associated FTO gene with well studied examples such as insulin and leptin." (PMID 26886906, 2016). "That is the case of the FTO (fat mass and obesity associated) gene and its association with obesity and related traits or the TCF7L2 gene and its association with T2DM." (PMID 26927084, 2016).
Obesity (continued). "In conclusion, we have shown that the FTO variant rs9939609 is associated with obesity and showed for the first time in Pakistan, with coronary artery disease." (PMID 26878843, 2016). "This study revealed the genetic association between rs9939609 SNP of FTO and obesity in a Romanian population, and to the authors’ knowledge, this is the first study to investigate this association in a Romanian population." (PMID 27196486, 2016). "FTO is the highest scoring GWAS variant for obesity in both adults and children and, notably, one of only a handful that associates with variation in phenotype as well as magnitude." (PMID 26824653, 2016). "Genome-wide association studies have identified variants within the FTO (fat mass and obesity associated) locus as the strongest predictors of obesity amongst all obesity-associated gene loci." (PMID 27560134, 2016). "Fat mass and obesity associated (FTO) is gene involved in obesity which affects more than 1/6 of the population worldwide." (PMID 27454254, 2016). "Understanding the neural correlates underpinning the association between one of the most studied obesity gene, such as the FTO, and the susceptibility to obesity, will help future research in developing individual-tailored strategies for obesity prevention." (PMID 26924971, 2016). "A recent study has demonstrated that obesity-associated non-coding variants in FTO affect the expression of the gene IRX3 in humans, mice and zebrafish." (PMID 26907388, 2016). "More recently, we demonstrated significant heritability estimates of obesity-related phenotypes in our Latino population, and confirmed strong associations to obesity-related traits for the FTO SNPs." (PMID 26908368, 2016). "Jia G FY, Zhao X, Dai Q, Zheng G, Yang Y, Yi C, Lindahl T, Pan T, Yang YG, He C.: N6-methyladenosine in nuclear RNA is a major substrate of the obesity-associated FTO." (PMID 27454254, 2016). "In this study, we identified metabolites significantly associated with obesity and T2D based on FTO genotype in 2,577 individuals from the KARE cohort." (PMID 27249024, 2016). "Another review article is describing the role of FTO gene, which is associated with obesity in humans and has been identified as the first gene related to obesity in human from the genome-wide association study." (PMID 27293434, 2016). "FTO gene variants, rs8050136 and rs11076023, have been shown to be associated with obesity and T2D, respectively, in the CURES study." (PMID 27274759, 2016). "In 2007, the fat mass and obesity associated (FTO) gene was discovered and found to be significantly associated with both children and adults obesity." (PMID 26964098, 2016). "This study provides the first evidence about the association of FTO rs9939609/rs17817449 AA/GG with obesity in this population." (PMID 27196486, 2016). "Among of the five PC metabolites associated with obesity and T2D based on FTO genotype, four (PC aa C36:5, C38:5, C38:6, and C40:6) are associated with apolipoprotein B (ApoB)." (PMID 27249024, 2016). "For the most relevant obesity polygene FTO, our data are comparable to previous studies as we also detected non-synonymous variants in both obesity and control study groups." (PMID 26828654, 2016). "Our finding is in accordance with the previous large studies among Europeans where physical activity was shown to attenuate the risk of FTO risk allele on obesity." (PMID 27274759, 2016). "Genome-wide association studies linked common variants of FTO gene with childhood and adult obesity in 2007." (PMID 27249342, 2016). "Genome wide association studies (GWAS) have been instrumental in the discovery of genes associated with obesity, including the fat mass and obesity-associated (FTO) gene." (PMID 26907388, 2016). "In another study, the association between FTO rs9939609 SNP and obesity was seen in children from 7 to 9 years old, in whom A allele was linked with body weight as well as fat mass." (PMID 27196486, 2016).
Obesity (continued). "Multiple studies have focused on deciphering potential mechanisms, by which variants within a region of high linkage disequilibrium in introns 1 and 2 of FTO confer the obesity risk." (PMID 27560134, 2016). "We identified seven metabolites that were significantly associated with obesity and T2D based on FTO genotype." (PMID 27249024, 2016). "Variants in the fat mass and obesity–associated gene FTO have been identified as the strongest common genetic risk factors for obesity and T2D." (PMID 27249024, 2016). "The FTO rs9939609 polymorphism was found to be significantly associated with obesity as well as CAD in Pakistani subjects." (PMID 26878843, 2016). "Identifying and understanding the mechanisms that underlie the relationship between FTO and obesity will facilitate the development of rational strategies for personalized management of this metabolic disease." (PMID 26726774, 2016). "The obesity risk gene FTO encodes a 2-oxoglutarate-dependent nucleic acid demethylase, that is expressed in several peripheral tissues as well as in brain regions affecting energy balance." (PMID 27846319, 2016). "We investigated the association of six SNPs distributed along intron 1 of FTO gene: rs7191566, rs1121980, rs1781449, rs3751812, rs9930506, and rs8044769, with obesity in a cohort of Mexican Mestizos (MMs)." (PMID 26726774, 2016). "There is evidence that physical activity (PA) can attenuate the influence of the fat mass- and obesity-associated (FTO) genotype on the risk to develop obesity." (PMID 26851191, 2016). "Significant associations were found between FTO rs9939609 single nucleotide polymorphism (SNP) and obesity." (PMID 27196486, 2016). "Our data attest the previously reported association regarding the genetic variability in intron 1 of FTO gene and obesity risk." (PMID 27196486, 2016). "These sex-based differences in the heritability of an increased BMI are consistent with previous studies that reported that FTO association with obesity traits occurs independently in males and females." (PMID 26726774, 2016). "Obesity-associated FTO intron has been reported to contain enhancers and spatially connect with IRX3 in both human and mouse." (PMID 26868054, 2016). "Genome-wide association studies have shown that variants in fat mass and obesity-associated (FTO) gene are robustly associated with body mass index and obesity." (PMID 26727661, 2016). "Among the polymorphisms with known association with obesity, the most important are the FTO 1st intron variants." (PMID 27237450, 2016). "Of these, the fat mass and obesity–associated gene (FTO) variants were found to be consistently associated with obesity-related traits in several populations and has been the strongest common genetic predictor of obesity known so far." (PMID 27274759, 2016). "A recent investigation documented ethnicity-dependent differences in genetic susceptibility to obesity across populations, they reported evidence of a higher impact of FTO on Caucasians than on Chinese, African, and Hispanic populations." (PMID 26726774, 2016). "The analysis of genotypes with obesity-relatedcharacteristics found that FTO was associated with BMI (β = 0.46, p =0.03), waist circumference (β = 0.03, p = 0.02), triceps skinfold (β = 0.08, p = 0.03)and waist/height ratio (β = 0.03, p = 0.01)." (PMID 27560839, 2016). "The fat mass and obesity associated gene (FTO) harbors GWAS derived polygenic variants with the largest effect size on BMI (FTO;)." (PMID 26828654, 2016). "For example, miR-4284, identified only in humans and not yet associated to any function in adipocytes, have as predicted targets in silico the well-known obesity associated gene FTO." (PMID 27345691, 2016). "The strongest genetic association with risk to polygenic obesity are single-nucleotide variants (SNV) in intron 1 and 2 of the FTO (fat mass and obesity associated) gene." (PMID 26950145, 2016).
Obesity (continued). "Most of these genes likely to be essential in nature, whereas some of the recently reported candidate genes are present in periphery in our map, e.g. fat mass and obesity associated (FTO) gene." (PMID 26886906, 2016). "The FTO gene was the first gene with common variants that affect susceptibility to obesity in the general population." (PMID 27275782, 2016). "Because of the high incidence of childhood obesity in our country, we tested the association of the FTO rs9939609 and rs17817449 SNP with some obesity-related anthropometric and metabolic parameters in a large children cohort." (PMID 27196486, 2016). "This indicates that PA is associated with a 36–51% decrease in the effect of FTO rs1421085 on obesity measures at baseline." (PMID 26727462, 2016). "Variants in the FTO (fat mass and obesity-related) gene have been associated with body mass index and waist and hip circumferences in widespread populations." (PMID 27196486, 2016). "Genome-wide association studies have shown that variations in the first intron of the Fat mass and obesity associated (FTO) gene are associated with obesity and diabetes in global studies of different ethnicities." (PMID 26727661, 2016). "The link between the FTO gene polymorphism and obesity has been confirmed in several populations, although no data on Romanian children are available." (PMID 27196486, 2016). "Despite large size of FTO gene, variants implicated in obesity and weight gain are largely located in the first intron." (PMID 26878843, 2016). "Previous study in the South Indian population (CURES) has shown that the FTO SNPs (rs1588413 and rs8050136) increased obesity risk by 1.27 and 2.06 times, which is equivalent to BMI increase by 0.33 and 0.54 kg/m2 per effect allele, respectively." (PMID 27274759, 2016). "The first reported association of an FTO variant with obesity and T2D was for variant rs9939609 in a European population." (PMID 27249024, 2016). "CRISPR also helped to pinpoint a specific single-nucleotide polymorphism (SNP) in the human FTO locus as the critical effector for obesity." (PMID 26880991, 2016). "Through comparison of various statistical methods, seven metabolites were identified that are significantly altered in obesity and T2D based on the FTO risk allele (adjusted p < 0.05)." (PMID 27249024, 2016). "A recent meta-analysis of data from eight Indian studies showed that FTO variant, rs9939609, increased the risk of obesity by 1.15 times, which is equivalent to BMI increase by 0.30 kg/m2 per effect allele." (PMID 27274759, 2016). "The authors reported an effect of the NYD-SP18 variants on obesity that was even larger than the effect of the FTO polymorphism." (PMID 27237450, 2016). "We identified the nominally significant associations with obesity for effect alleles of 6 SNPs at FTO, SEC16B, TFAP2B, RBJ, MAP2K5 and CDKAL1 (ORs for the effect allele ranged between 1.19 and 1.41, nominal two-sided P < 0.05)." (PMID 26800887, 2016). "The primary aim of this study was to investigate the association of obesity related SNPs (two FTO SNPs and one SNP near MC4R) with fetal growth throughout gestation in children of the Southampton Women's Survey (SWS)." (PMID 26907388, 2016). "Following the identification of obesity variants in FTO, a robust and replicated association between BMI and variants ~188 kb upstream of MC4R was reported [55, 58••, 85–87]." (PMID 26363598, 2015). "Fat mass and obesity-associated (FTO) gene plays a role in regulation of food intake and is originally identified as a susceptibility gene for obesity." (PMID 26146447, 2015). "Previous genome-wide association study (GWAS) in 2007 has identified a set of susceptibility loci within the first intron of FTO gene that are obesity-related." (PMID 26146447, 2015).
Obesity (continued). "Cross-sectionally, the FTO (fat mass and obesity associated) variant (rs1121980) was the only marker being significantly associated in sex and age-adjusted linear regression models with BMI after multiple testing." (PMID 26445370, 2015). "Single nucleotide polymorphisms (SNPs) within the Fat mass and obesity associated (FTO) gene have been linked with increased body weight." (PMID 26431034, 2015). "An obesity-associated SNP in intron 1 of FTO has been associated with decreased browning of white adipose tissue, which coincided with an increase in expression of IRX3 and IRX5 in preadipocytes." (PMID 26788058, 2015). "In this respect, the study of a number of obesity-affected families from our study groups was essayed with significant results on the inheritance of the FTO rs9939609 obesity predisposition." (PMID 25866584, 2015). "The sudden interest in a 40 year old discovery was due in part to the finding of FTO’s (Fat Mass Obesity) N6-methyl-adenosine (m6A) deaminase activity, thus suggesting a link between obesity-associated diseases and the presence of m6A in mRNA." (PMID 26186436, 2015). "Single nucleotide polymorphisms (SNPs) in the fat mass and obesity-associated gene (FTO) locus seem to be among the eminent factors associated with obesity measures such as body mass index (BMI)." (PMID 25647475, 2015). "Despite the metabolic phenotypes found in FTO overexpression/inactivation rodent models and the location of SNPs associated with human obesity in the intron 1 region of FTO, the implication of other neighboring genes in obesity is not excluded." (PMID 25825681, 2015). "Another recent study found that an obesity-associated SNP in intron 1 of FTO was located in a long enhancer region in preadipocytes specifically." (PMID 26788058, 2015). "The common FTO variants are associated with obesity in Pakistani population and exert their effect either by affecting energy regulation or altering lipid profile of the body." (PMID 26357660, 2015). "In 2007, the first gene described in association with the common obesity was the fat mass and obesity associated gene (FTO)." (PMID 25866584, 2015). "In future, more studies with larger sample size are needed to clarify the contradiction of age and gender association of FTO variants with obesity in Pakistani population." (PMID 26357660, 2015). "FTO was identified as an obesity susceptibility gene by several large-scale genome associationstudies." (PMID 26691922, 2015). "In 2007, several independent GWAS and population based approaches identified associations between SNPs in intron 1 of FTO and human obesity in various European populations." (PMID 26788058, 2015). "These compelling results suggest that the rs1421085 single-nucleotide change can alter metabolism that is responsible for the association between the first intron of FTO and obesity in humans." (PMID 26557137, 2015). "For example, the associations between TCF7L2, TSPAN8/LGR5, FTO and MetS T2D were attenuated when adjusted for BMI, suggesting the role of obesity." (PMID 26599349, 2015). "The fat mass and obesity associated gene (FTO) is the first gene that has been convincingly associated with obesity using GWAS." (PMID 25825681, 2015). "In our overlap analysis of obesity and osteoarthritis, a variant in FTO, which is established as associated with both traits, was the top signal based on both ABFs and on P‐values, which demonstrates the validity of our approach." (PMID 26411566, 2015). "Mouse models of increased IRX3 and IRX5 expression as well as in vivo models harboring the human mutations are necessary to fully understand the association between FTO intron 1 and obesity." (PMID 26557137, 2015). "In 2007, FTO was identified as the first genome-wide association study (GWAS) gene associated with obesity in humans." (PMID 26788058, 2015).